GRN (granulin precursor)
Diseases named in the same sentence as GRN in open-access papers (continued):
Sharing a sentence is not in itself a finding about the gene and the disease.
neurodegenerative disease (139 papers, 2011 to 2026). A disorder of the central nervous system characterized by gradual and progressive loss of neural tissue and neurologic function. "Loss-of-function mutations in the GRN gene were considered as causative factors for neurodegenerative diseases, like FTD and lysosomal storage disorders." (PMID 41155255, 2025). "Mutations in GRN, encoding progranulin (PGRN), represent another strong connection between lipidoses and neurodegenerative diseases." (PMID 40498021, 2025). "That GRN mutations are associated with other forms of neurodegenerative disease suggests a common mechanism for PGRN in protecting against neurodegeneration." (PMID 38643236, 2024). "It is therefore likely that the elevated FABP3 levels that we observe in microglia reflect a response to the lipid burden that microglia are facing in diseased conditions specifically upon GRN deficiency but also in other neurodegenerative diseases." (PMID 37775827, 2023). "For the sentinel SNP rs1990622, allele rs1990622A has been shown to act as a risk factor and rs1990622G is protective in FTLD with GRN mutations and other neurodegenerative diseases." (PMID 37146150, 2023). "Here, we prove the robustness and precise diagnostic performance of this kit, which accurately distinguishes GRN mutations carriers from other neurodegenerative disease patients and non-GRN mutation carriers." (PMID 37476993, 2023). "The impairment of autophagy caused by GRN mutations in neurons and immune cells can translate to increased risk of neurodegenerative disease with time." (PMID 33886609, 2021). "Because GRN had been known as a widely expressed growth factor with important roles in development, inflammation, and tumorigenesis, the discovery of GRN mutations in an adult onset neurodegenerative disease was surprising." (PMID 34366786, 2021). "Based on these data, plasma EV levels appear to increase in GRN mutation carriers in parallel with the onset of symptomatic neurodegenerative disease." (PMID 33197149, 2020). "GRN deficiency causes neurodegenerative diseases, namely frontotemporal dementia and neuronal ceroid lipofuscinosis." (PMID 31200555, 2019). "The 80-year-old brother who is still free of any clinical evidence of a neurodegenerative disease, continuing to manage independently all Instrumental Activities of Daily Living (IADLs) including driving, has the same GRN mutation as the patient." (PMID 26961809, 2016). "Due to PGRN's neuroprotective properties, identifying proteins or compounds to increase PGRN levels is a key therapeutic avenue, not only for FTD patients with loss-of-function GRN mutations, but also for other neurodegenerative diseases." (PMID 27356620, 2016). "Is risk for late onset neurodegenerative disease from mutation in GBA or GRN related to gene-product specific mechanisms?" (PMID 26869920, 2016). "A loss of PGRN expression, and therefore function, is associated with increased risk for neurodegenerative diseases, and understanding mechanisms associated with GRN deficiency may aid in future therapeutic development." (PMID 40200337, 2025). "Finally, we tested SMAD3, another candidate TF from our transposon experiments, and GRN, a secreted growth factor linked to lysosomal function and multiple neurodegenerative diseases." (PMID 41311869, 2025). "These insights could potentially shed light on the underlying mechanisms of neurodegenerative diseases linked to GRN mutation and offer new avenues for therapeutic interventions." (PMID 38191490, 2024). "Similarly, polymorphisms in the GRN gene have also been associated with neurodegenerative diseases, including frontotemporal dementia." (PMID 37863893, 2023). "More recently, a meta-analysis was performed in 16 case study to investigate the link between the GRN polymorphism at rs5848 with neurodegenerative diseases, such as FTD, AD, PD, and ALS, and the authors conclude that the polymorphism at rs5848 is associated with a higher risk of AD and PD." (PMID 38037070, 2023).
neurodegenerative disease (continued). "It is important to note that laterality occurs at various stages of neurodegenerative disease progression, which may increase the variability in atrophy rates in individual GRN mutation carriers." (PMID 32184751, 2020). "Interestingly, deregulated microglial activation plays a key role in neurodegenerative diseases caused by GRN deficiency." (PMID 31200555, 2019). "Reduced serum level of the progranulin was identified in homozygous GRN rs5848 T-allele carriers, supporting the hypothesis that GRN rs5848 affects the risk of neurodegenerative diseases by regulating GRN expression." (PMID 23342160, 2013). "Since PSAP and GRN are both lysosomal genes, we hypothesize that biallelic rare variants of these genes are causing severe rare diseases, while the monoallelic rare variants may play role in the development of common neurodegenerative diseases." (PMID 35752680, 2022). "The high frequency of concomitant pathologies in GRN mutation carriers, such as the combination of FTLD with PD or FTLD with AD, might indicate that loss or partial loss of GRN could advance pathological features of other neurodegenerative diseases in an early stage." (PMID 29370838, 2018). "Deficiency in PGRN levels is associated with development of neurodegenerative disease, including FTD subtypes with a mutation in C9ORF72 (TDP type A/B) and in GRN (TDP type B), and is linked to lysosomal dysfunction and TDP-43 aggregation." (PMID 40713859, 2025). "In particular, pathogenic mutations in genes that encode lysosomal or lysosome-associated proteins (e.g., GRN, LRRK2, GBA, TMEM106B, C9orf72) are major causes of inherited neurodegenerative diseases." (PMID 37974165, 2023). "Serum PGRN levels, GRN rs5848 polymorphism, and GRN mutations were evaluated in 239 participants (22 cognitively unimpaired participants and 217 patients with neurodegenerative diseases)." (PMID 35085262, 2022). "Progranulin (PGRN) protein, encoded by the granulin (GRN) gene, has been implicated in several neurodegenerative diseases." (PMID 35120524, 2022). "All but one patient (P1) showed the presence of variants already identified as risks factors for neurodegenerative diseases, rs662 (PON1) and rs5848 (GRN)." (PMID 34946792, 2021). "GRN seems to play an important role in multiple neurodegenerative diseases including PD, likely due to its function as a neurotrophic factor and its recently uncovered lysosome function." (PMID 29692703, 2018). "Notably, GRN variants have also been identified in patients with AD and PD, indicating a broader relevance for PGRN in more common neurodegenerative diseases." (PMID 40498021, 2025). "The precise mechanism by which GRN and TMEM106B variants affect brain aging and whether the relevant pathways also contribute to an increased risk for neurodegenerative diseases are currently unclear." (PMID 40713630, 2025). "Three variants in GRN, including two loss of function variants (including p.Q130fs and p.Y294X) and one splicing variant (c.708+6_708+9del), have been previously reported to cause FTD, FTLD, and neurodegenerative disease." (PMID 39606324, 2024). "Interestingly, SEMA3F and GRN/Progranulin are new therapeutic targets for neurodegenerative diseases and CNV." (PMID 38115754, 2024). "We next asked if these unique features of human neurodegenerative disease progress over time in GRN−/− mbOrgs, as would be expected if these features represent cellular mechanisms that could be relevant to human disease progression." (PMID 36827976, 2023). "However, GRN and TMEM106B have also been linked to brain health and many other neurodegenerative diseases." (PMID 35379992, 2022). "Although GRN and TMEM106B were initially identified as genes associated with FTLD, these two genes have been intimately linked to brain health and associated with many other neurodegenerative diseases." (PMID 32852886, 2020). "Besides FTLD, GRN and TMEM106B have been implicated in brain aging and many other neurodegenerative diseases." (PMID 32852886, 2020).
neurodegenerative disease (continued). "We identified 70 additional novel and missense variants in other genes, such as MAPT, GRN, CSF1R, and PRNP, related to neurodegenerative diseases, which may represent overlapping clinical and neuropathological features with AD." (PMID 31182772, 2019). "In addition, the role of m6A methylation in neural development and neurodegenerative diseases indicates that it may overlap with the role of the GRN gene in nervous system diseases." (PMID 40736401, 2025). "A common GRN polymorphism associated with risk for AD and FTD modestly reduces progranulin levels, indicating that even mild reduction of progranulin may increase risk for neurodegenerative disease." (PMID 41178544, 2025). "Haploinsufficiency of PGRN, caused by heterozygous loss-of-function mutations in 1 GRN allele, leads to the development of autosomal dominant familial frontotemporal lobar degeneration (FTLD), a neurodegenerative disease characterized by atrophy of the frontal and temporal lobes of the brain." (PMID 34618685, 2021). "Thus, although the contribution of GRN SNPs to neurodegenerative diseases has not been elucidated, our present finding suggests that GRN is associated with survival after onset in carriers of C9ORF72 repeat expansions (p-value = 0.001)." (PMID 25239657, 2014). "Since little is known about TMEM106B and its expression in human brain, we performed immunohistochemical studies of TMEM106B in postmortem human brain samples from normal individuals, FTLD-TDP individuals with and without GRN mutations, and individuals with other neurodegenerative diseases." (PMID 24252750, 2013). "The proteins upregulated across multiple neurodegenerative diseases within cortical layer I include phosphorylated TDP-43 (significant change identified in C9ORF72 and GRN) and phosphorylated tau S214 (significant change identified in AD and MAPT)." (PMID 40476255, 2025). "Taken together, our strategy reveals the cell-type-specific basis of splicing and gene expression dysregulation in GRN-FTD and provides a means to shed further light on all neurodegenerative diseases." (PMID 40913764, 2025). "Similarly to previous tested PGRN plasma assays, in this study, comparing PGRN levels between different neurodegenerative diseases show significant distinction from GRN mutation and non-GRN mutation carriers, without any differences from symptomatic to non-symptomatic GRN mutation carriers." (PMID 37476993, 2023). "Our work applying HSPC-GT in murine models of neurodegenerative disease shows that for both GBA-PD and GRN-FTD, engrafted cells have the capacity to produce potentially therapeutic proteins at significant levels." (PMID 35614857, 2022). "In this study, we have provided an initial characterization of TMEM106B protein expression in normal, GRN (−) FTLD-TDP, and GRN (+) FTLD-TDP human brain, as well as other neurodegenerative disease controls." (PMID 24252750, 2013). "In addition to GRN and TMEM106B, many other lysosomal genes are directly involved in neurodegenerative diseases and lysosomal dysfunction has emerged as a common mechanism for neurodegeneration." (PMID 32852886, 2020). "As GRN was associated with regulating the lysosomal pathway in studies on neurodegenerative diseases, increased cytoplasmic GRN levels could be of relevance in CLL and one can hypothesize, that secreted GRN is just a side effect." (PMID 31200555, 2019). "Subjects were screened for C9orf72 repeat expansions, GRN and MAPT mutations, and, if negative, mutations in other neurodegenerative disease genes, by whole-exome sequencing (WES) (n = 108), including WES-based copy-number variant (CNV) analysis." (PMID 28749476, 2018). "For clinical validation, PGRN levels were measured in plasma from 32 cognitively healthy individuals, 52 confirmed GRN mutation carriers, 25 C9orf72 mutation carriers and 216 patients with different neurodegenerative diseases of which 70 were confirmed as non-mutation carriers." (PMID 37476993, 2023).
tumor (98 papers, 2009 to 2026). "In the interaction between fibroblasts and macrophages, the macrophage subpopulation supporting tumor angiogenesis exhibits significant activity in ER+BC, with the associated SPP1 and GRN pathways strongly influencing tumor progression." (PMID 41635010, 2026). "MIC-1 (GDF15) and GRN are associated with tumor-induced immune tolerance and inflammation, while MERTK is a receptor tyrosine kinase involved in the clearance of apoptotic cells and immune suppression." (PMID 40805206, 2025). "Single-cell RNA-seq analysis of human SCLC tumors revealed that GRN was highly expressed in alveolar macrophages (AMs) and tumor-associated macrophages (TAMs), especially in patients with progressed disease." (PMID 39910394, 2025). "The results also revealed a putative mechanism and association between GRN and tumor-immune interactions." (PMID 37091137, 2023). "As CLL was shown to be associated with an accumulation of monocytes and a tumor-protective myeloid cell skewing, this suggests that GRN secretion by tumor-educated myeloid cells confounds GRN elevation in CLL patients’ serum." (PMID 31200555, 2019). "Of note, high GRN was statistically significantly associated with shorter progression-free survival, increased tumor-associated deaths, and shorter overall survival of the patients." (PMID 31200555, 2019). "GRN and its associated genes were linked to cancer cell intrinsic immunogenicity, and single-cell RNA-seq data revealed that GRN expression is particularly high in subsets of tumor-associated macrophages." (PMID 39910394, 2025). "The expression of GRN by pRMS macrophages might be linked to dedifferentiation and proliferation of tumor cells, as suggested by previous studies." (PMID 41373578, 2025). "PTMS may complement current clinicopathologic factors for risk stratification, and GRN emerges as a tumor- or stroma-intrinsic node with therapeutic potential." (PMID 41488055, 2025). "Thus, we may conclude that CTHRC1 may induce tumor associated macrophage infiltration though GRN/TNFRSF1A and AnxA1/FPR1 pathways." (PMID 35928443, 2022). "While the loss of GRN is primarily associated with neurodegeneration, the biological functions of the secreted growth factor-like protein are more diverse, ranging from wound healing, inflammation, vasculogenesis, and metabolic regulation to tumor cell growth and metastasis." (PMID 34366786, 2021). "Together, they point to a tumor- or stroma-centric axis through which GRN drives immune suppression and malignant aggressiveness in OS." (PMID 41488055, 2025). "We found through single-cell sequencing analysis that the high-risk group was primarily enriched in GRN, TWEAK, and KIT tumor-related signaling pathways." (PMID 41211507, 2025). "Functionally, GRN knockdown curtailed proliferation, clonogenicity, migration, and invasion of OS cells, supporting a tumor-promoting role." (PMID 41488055, 2025). "GRN emerges as a tumor- and stroma-intrinsic mediator of immune suppression and malignant traits and represents a biologically grounded target for future mechanistic and therapeutic studies." (PMID 41488055, 2025). "Ligands secreted by START, such as GAS6 and ICAM, lead to a protumoral phenotype acquisition (M2 phenotype) in the IMs, while CXCL2 and GRN, secreted by IMs, trigger tumor growth in START." (PMID 38546390, 2024). "We also employed Tumor Immune Estimation Resource (TIMER) to examine the data set of GRN expression and immune infiltration level in GBM and investigate the cumulative survival in GBM." (PMID 37091137, 2023). "Increased GRN expression was shown to have a significant relationship to tumor grade in a univariate study utilizing logistic regression." (PMID 37091137, 2023). "Similar associations have been found between GRN expression and various immune cell markers, suggesting a pivotal role of GRN in controlling the GBM tumor immunological microenvironment." (PMID 37091137, 2023).
tumor (continued). "For example, the engineered CRISPR-dCas9 system has been used for targeting the Granulin (GRN) gene, a growth factor that promotes tumor progression in liver cancer." (PMID 36672870, 2023). "The 160 tumor samples were divided into GRN high expression group and GRN low expression group according to the median GRN expression level." (PMID 37091137, 2023). "To see if LGALS9, HBEGF, and GRN mediate tumor-macrophage interactions and contribute to PDAC progression, we performed in vitro experimental studies for validation." (PMID 36864399, 2023). "We found CAFs which highly expressed CTHRC1 (from F04 and F08) and tumor associated macrophages were mediated by a different set of ligand-receptor pairs, including THY1/aXb2 complex, GRN/TNFRSF1A, CD99/PILRA, CD74/MIF, APP/CD74, ANXA1/FPR1, etc." (PMID 35928443, 2022). "More importantly, the phenotypes of GRN- and EphA2-deleted cells were very different in terms of cell migration, invasion, adhesion and in vivo tumor formation." (PMID 36471440, 2022). "GRN seems to stimulate tumor growth and promotes tumor cell migration, invasiveness, anchorage independence, and chemo-resistance." (PMID 34366786, 2021). "MiR-107 overexpression in tumor cells efficiently suppressed GRN expression and proliferative activity." (PMID 32883962, 2020). "Analysis of tumour tissues from a cohort of patients with BC revealed that high GRN expression correlated with the most aggressive triple-negative BLBC and reduced patient survival." (PMID 29921315, 2018). "Granulin (GRN) contributes to multiple human cancers in a way that potentates neoplastic transformation, stimulates tumor growth, metastases, and inhibits anti-apoptotic mechanisms." (PMID 29286311, 2017). "In the classical signal transduction pathway of VEGFA in promoting angiogenesis, GRN is involved in three kinase pathways that regulate tumor growth (MAPK, P13K, and FAK)." (PMID 24349832, 2013). "One of the issues with gene therapies is that GRN was categorized as an oncogene; its overexpression may promote tumor progression." (PMID 41155255, 2025). "For GRN-low patients, combined chemo-immunotherapy offers significant survival benefits, while for GRN-high patients, novel approaches targeting the tumor microenvironment or GRN-driven pathways may be required to overcome resistance." (PMID 39910394, 2025). "Furthermore, the high risk group was primarily enriched in GRN, TWEAK, and KIT tumor-related signaling pathways." (PMID 41211507, 2025). "GRN stimulated tumor cell proliferation, migration, and invasion." (PMID 38600248, 2024). "GRN is upregulated in neoplastic tissues, and has a pro-tumorigenic role by promoting cancer cell proliferation, migration, invasiveness, anchorage-independent growth, modulation of the tumour microenvironment, immune evasion and resistance to chemotherapy." (PMID 38212481, 2024). "Also, LGALS9, HBEGF, and GRN were confirmed to be over-expressed in macrophage subset, highlighting the potential roles in mediating tumor-macrophage interactions." (PMID 36864399, 2023). "GRN expression was shown to be correlated with tumor stages in TCGA analysis using R-4.2.1." (PMID 37091137, 2023). "We found that the tumor had higher GRN expression than normal." (PMID 37091137, 2023). "Finally, we demonstrated that TAMs directly regulated tumor cells through GRN and MIF signaling pathways, while regulated themselves through inhibition of CCL and GALECTIN signaling pathways during the invasion process." (PMID 35523772, 2022). "Notably, GRN KO cells generated tumors with significantly higher tumor volume as compared to both parental and EphA2 KO MSTO-211H cells." (PMID 36471440, 2022). "Finally, we identified that TAMs regulated tumor cells through GRN and MIF signaling pathways, while TAMs self-regulated through inhibition of CCL and GALECTIN signaling pathways during the invasion process." (PMID 35523772, 2022).